GDNF (glial cell derived neurotrophic factor)
Diseases named in the same sentence as GDNF in open-access papers (continued):
Sharing a sentence is not in itself a finding about the gene and the disease.
Stroke (continued). "However, there are no studies that have evaluated the effects of a single or multi-session exercise on serum IGF-II or GDNF levels in people with stroke." (PMID 36556107, 2022). "Our study also demonstrated that injection of RGD-PLT@PLGA-FE delivered BDNF, bFGF and GDNF to mice brain after stroke, which could contribute to angiogenesis and neurogenesis, and subsequently improved neurobehavioral recovery." (PMID 35642036, 2022). "The mouse TfRMAb-GDNF fusion protein was also neuroprotective in the MACO stroke model." (PMID 35890374, 2022). "Additionally, intracerebral infusion of GDNF promotes striatal neurogenesis after stroke and CNTF has been shown to promote the development of neurons and glial cells and prevent ischemia-reduced neuronal loss in gerbils." (PMID 36076942, 2022). "In another rat model study, treatment with levodopa enhanced functional recovery after experimental stroke, accompanied with an increase of GDNF level in the ischemic hemisphere, suggesting involvement of GDNF in the mechanisms of tissue reorganization and plasticity." (PMID 28819313, 2017). "In addition, transplantation of neural stem cells overexpressing GDNF enhanced neurogenesis in rats after stroke." (PMID 25045659, 2014). "Moreover, these grafted neural stem cells modified by the GDNF gene had higher survival rates and differentiation after stroke, less apoptosis, and greater expression of BDNF and NT-3." (PMID 23251608, 2012). "For example, GDNF increased migration and differentiation in animal stroke models." (PMID 23251608, 2012). "Moreover, HIRmAb-GDNF activity has been previously documented in cell culture assays and in a rat model of stroke, using direct intracerebral injection." (PMID 22745701, 2012). "Data obtained from in vivo studies indicated that GDNF and its receptors are widely expressed in the rat hippocampus; furthermore, stroke, traumatic brain injury, or kainate-induces seizures significantly increases GDNF and their receptors mRNA expression in this limbic region." (PMID 19649251, 2009). "GDNF could also protect the hippocampus against excitotoxic damage in rats after stroke." (PMID 38008847, 2023). "In addition, various neurotrophic factors secreted by astrocytes, such as nerve growth factor (NGF), brain-derived growth factor (BDNF), erythropoietin (EPO), vascular endothelial growth factor (VEGF), and glial derived neurotrophic factor (GDNF), are increased after stroke." (PMID 36159395, 2022). "Chronic stress leads to a decrease of GDNF, yet acute stress of stroke may lead to the opposite." (PMID 28819313, 2017). "Moreover, neural crest-derived stem cells have been proved to secrete several active factors such as brain-derived neurotrophic factor (BDNF), basic fibroblast growth factor (bFGF), and Glial cell line-derived neurotrophic factor (GDNF) to enhance neurogenesis in brain after stroke." (PMID 25883981, 2015). "Specifically, GDNF appears to mitigate excitotoxic neuronal death through an ERK-dependent pathway, making early administration crucial in the treatment of stroke." (PMID 40642294, 2025). "The interaction between FE particles coated with RGD-PLT facilitates the sustained release of FE at the stroke site, delivering the neurotrophic factors BDNF, GDNF, and bFGF to the brain." (PMID 37445979, 2023). "DAPs can also significantly upregulate the expression of glial cell derived neurotrophic factor (GDNF) and nerve growth factor NGF, suggesting the neuroprotective effect of DAPs after stroke." (PMID 36235835, 2022). "Further research is needed to elucidate the factors that influence changes in BDNF, GDNF and IGF-II levels in people with stroke receiving physical therapy and chiropractic adjustments." (PMID 36556107, 2022). "The neurotrophic factors transcripts including BDNF, GDNF, NGF, and NT‐3 were measured 7‐day post‐stroke." (PMID 35715988, 2022).
Stroke (continued). "The AUCs for lipocalin-2, sP-selectin, glial cell-derived neurotrophic factor (GDNF), sVCAM-1, sRAGE, MMP-7, D-dimer, MMP-1, Apolipoprotein CIII, myoglobin and BNDF were ≥0.75 in predicting stroke amongst children with TBM." (PMID 33930055, 2021). "Activated reactive astrocytes protect neurons after stroke by producing a variety of neurotrophic factors, including nerve growth factor, basic fibroblast growth factor, BDNF, and glial cell–derived neurotrophic factor." (PMID 34234667, 2021). "Memantine improved stroke outcomes via increasing BDNF, GDNF, and VEGF levels, reducing reactive astrogliosis and enhancing vascular density." (PMID 32782018, 2020). "Intracerebral infusion of growth factors, such as glial cell line derived neurotrophic factor (GDNF), enhanced striatal neurogenesis in the SVZ, but also improved the survival of cells migrating into the stroke-damaged striatum." (PMID 31787865, 2019). "Based on these results and on the efficacy of direct triple gene therapy for stroke we proposed to enhance the therapeutic potential of UCB-MC via simultaneous transduction of UCB-MC with Ad-VEGF, Ad-GDNF, and Ad-NCAM." (PMID 29497380, 2018). "Immunofluorescent analysis revealed expression of VEGF, GDNF, and NCAM in neural and glial cells at the site of stroke." (PMID 29497380, 2018). "The current study is designed as a proof-of-principle to investigate the therapeutic efficacy of in vivo and ex vivo triple gene therapy (VEGF, GDNF, and NCAM) for increasing survivability of the affected neurons in a rat model of stroke." (PMID 29497380, 2018). "In the studies with animal models of stroke, an increase in the expression of BDNF, GDNF, HGF, EGF, FGF-2, and IGF-1, as rapidly as 12 h after the insult and lasting until 5 days after stroke, has been described." (PMID 26607630, 2016). "Overexpression of growth factor genes including VEGF, GDNF, BDNF, and Akt1 was able to significantly promote the survival of NSCs in stroke animal model." (PMID 24719869, 2014). "This longer oxygen cycling (treated stroke by HBO for repetitive schedules for 3 weeks) therapy orchestrated gliosis and trophic factor production (BDNF, NGF, and GDNF) and decreased harmful effects by neutrophils in the early phase." (PMID 23533308, 2013). "Infusion of glial-derived neurotrophic factor (GDNF), a member of the TGF-β family, into ischemic striatum promoted neurogenesis after stroke." (PMID 22628111, 2012). "Endogeneous or exogenously injected neurotrophic factors including BDNF, GDNF, CNTF and NT3 had neuroprotective effect in damaged brain including stroke." (PMID 18060066, 2007). "There was a positive relationship between the severity of stroke at D1 according to the National Institutes of Health Stroke Scale, and ADEV AQP4 at D1 (r = 0.50, p = 0.031), as well as ADEV GDNF at D1 and D7 (r = 0.49, p = 0.035 and r = 0.53, p = 0.021, respectively)." (PMID 39596535, 2024). "IV etanercept or GDNF are not neuroprotective in experimental stroke because these biologics do not cross the BBB, and because the BBB is intact in the early hours after stroke, when neuroprotection in stroke is possible." (PMID 35745855, 2022). "Furthermore, cotreatment with TfRMAb-GDNF and TfRMAb-TNFR following MCAO enhanced neuroprotection, reducing the cortical stroke volume to 69%." (PMID 35890374, 2022). "Neurotrophic factors from NGF (nerve growth factor), GDNF (glial cell-derived neurotrophic factor), and BDNF (brain-derived neurotrophic factor) may attenuate the neurotoxic inflammatory response after a stroke." (PMID 33042113, 2020). "Indeed, genetic manipulation of neurotrophic factor expression, such as nerve growth factor (NGF) or glial-derived neurotrophic factor (GDNF) overexpression, have shown success in experimental models of clinical diseases including stroke." (PMID 33323541, 2020).
Stroke (continued). "Furthermore, exogenous administration of GDNF and BDNF reduced the toxic effects of excitatory amino acids, attenuated nitric oxide production, and lowered apoptosis/cell death in stroke animal models." (PMID 26706245, 2016). "Growths factors have been applied in stroke regeneration such as BDNF, GDNF and EPO." (PMID 25984331, 2014). "Previous studies demonstrated that GDNF improves behavioral functions, promotes neurogenesis, reduces infarct size, increases synaptic plasticity, and decreases apoptosis when applied as a recombinant protein, a TAT-fusion protein or via a viral vector in the post-acute phases of stroke." (PMID 34773698, 2022). "Similar to etanercept alone, GDNF alone had no neuroprotective effect in experimental stroke." (PMID 35745855, 2022). "Both these therapeutic pathways may be inert properties of MSCs and hypothermia, but may also be facilitated by delta opioids outside the ligand-receptor regulatory mechanism, as seen in GDNF upregulation and suppression of apoptotic cell death in DADLE-treated experimental stroke animals." (PMID 23077646, 2012). "We subsequently explored whether the amount of AQP4 and GDNF in the EV cargo correlated with the severity of neurological deficit, assessed by the NIHSS score at D1, D7, and M1, or with the short-term outcome according to the mRS score at D7 and M1 following stroke onset." (PMID 39596535, 2024). "In addition, we observed trends (0.05<p-value≤0.09) in increased levels of GDNF, interleukin (IL)-7, MMP-9, lipocalin-2, IL-4, sP-selectin, and myoglobin, and lower levels of CC5a, in children with TBM-related stroke compared to TBM without stroke." (PMID 33930055, 2021). "9cRA marginally enhanced the expression of BMP7, but not GDNF or BDNF, in the SVZ of stroke rats." (PMID 28674431, 2017).
glioma (82 papers, 2004 to 2025). A benign or malignant brain and spinal cord tumor that arises from glial cells (astrocytes, oligodendrocytes, ependymal cells). "Glioma stem cells express the receptor for the glial cell-derived neurotrophic factor, and mutations can result in the glial cell-derived neurotrophic factor and signal transduction pathways constitutively active in GBM cells." (PMID 39199662, 2024). "Recent studies have shown that the tumorigenesis of glioma is associated with the abnormal expression of many cytokines, including GDNF." (PMID 37594930, 2023). "In order to elucidate the molecular mechanism and target underlying the GDNF-induced C6 glioma cell proliferation, the C6 cells were incubated with 40 ng/ml GDNF for 0 h, 0.5 h, 1 h, and 24 h, respectively." (PMID 37594930, 2023). "Recent studies have shown that GDNF is associated with the development of gliomas and other cancers." (PMID 37594930, 2023). "The activity of the compounds to increase GDNF release on glioma cells and to inhibit the proliferation of pathogenic trypanosomes was tested." (PMID 35164094, 2022). "We had previously reported that GDNF contributes to glioma progression, while GDNF has also been linked to the activation of kinases in favor of glioma." (PMID 32050972, 2020). "GDNF is an important factor for invasive glioma cell growth; however, the underlying mechanism involved is unclear." (PMID 28212546, 2017). "Our findings provide new clues to the mechanism underlying abnormally high transcription of GDNF in glioma cells." (PMID 28187447, 2017). "The present study showed that treatment with AUR significantly increased the release of glial cell line-derived neurotrophic factor (GDNF), in a dose- and time-dependent manner, by rat C6 glioma cells, which release was associated with increased expression of GDNF mRNA." (PMID 31905925, 2019). "Furthermore, the GDNF–GFRA/RET pathway has been implicated in glioma models and may contribute to resistance/initiation of aggressive phenotypes." (PMID 41517303, 2025). "Testosterone upregulates glial cell line-derived neurotrophic factor (GDNF) in glioma cells and astrocytes essential for microglial proliferation, migration, and invasion." (PMID 40893157, 2025). "Using its interaction with its cognate receptor, GDNF receptor-α1, GDNF directly contributes to the growth of gliomas." (PMID 40727443, 2025). "The GDNF released by gliomas in humans and rodents acts as a potent chemotactic factor for brain-resident macrophages or, microglia." (PMID 40727443, 2025). "On the other hand, serotonin increases GDNF expression and secretion from C6 rat glioma cells, acting predominantly via 5-HT2A receptors." (PMID 40642294, 2025). "On the other hand, accumulating evidence demonstrates that GDNF is abundantly expressed in gliomas, especially in glioblastomas, and is a potent proliferation factor involved in the development and migration of gliomas." (PMID 38612708, 2024). "As a result of high GDNF activity, microglia are attracted to the tumor microenvironment to promote glioma progression." (PMID 38612708, 2024). "Wiesenhofer and colleagues found an abnormal elevation of GDNF expression in primary glioma tissues and multiple glioma cell lines." (PMID 37594930, 2023). "Mechanically, testosterone treatment regulates GDNF translocation from the glioma cells and astrocyte nuclei to the cytoplasm." (PMID 37833789, 2023). "Testosterone upregulates GDNF in glioma cells and astrocytes essential for microglial proliferation, migration, and invasion." (PMID 37833789, 2023). "Due to the neuroprotection conferred by GDNF in central nervous system cancers, its upregulation in testosterone-treated glioma cell lines and mice tissue protects glioma cell lines against immune response." (PMID 37833789, 2023).
glioma (continued). "In this study, we found CXCL1 was a proliferation-related gene by RNA-seq together with bioinformatics technology, and exogenous GDNF up-regulated the level of CXCL1 in rat C6 glioma cells determined by sqPCR and ELISA." (PMID 37594930, 2023). "For example, GDNF which is released by glioma cells can promote tumor growth, an action that is dependent on the presence of microglia." (PMID 36825022, 2023). "The knockdown of GDNF or its receptor in glioma cells significantly reduces tumor progression in vitro." (PMID 36825022, 2023). "In order to clarify the GDNF gene target responsible for promoting C6 glioma cell proliferation, we employed RNA-Seq analysis." (PMID 37594930, 2023). "Together, our results indicated that testosterone regulates GDNF and cytokine upregulation in glioma." (PMID 37833789, 2023). "Glioma cell line (U251) and human astrocytes (HA) DNA sequencing through next-generation sequence showed that GDNF, chemokine, and pro-inflammatory cytokine expression significantly increased in the testosterone-treated group compared with the untreated group." (PMID 37833789, 2023). "To determine the role of GDNF on the immune response to inflammation and glioma cell survival in vivo, we knock down the GDNF gene and proceed to pro-inflammatory protein detection via western blot." (PMID 37833789, 2023). "Glial cell-derived neurotrophic factor (GDNF) was originally isolated from the supernatant of a rat glioma cell line and found to have pronounced effects on the survival of midbrain dopaminergic neurons." (PMID 36835277, 2023). "Our study demonstrated that testosterone activates GDNF to protect the glioma cell line by inducing neuro-inflammation necessary for tumor development." (PMID 37833789, 2023). "In the previous experiments, our team confirmed that exogenous GDNF is able to promote the proliferation of rat glioma C6 cells in vitro." (PMID 37594930, 2023). "The new iboga series was investigated for its potential to promote the release of glial cell line-derived neurotrophic factor (GDNF) by C6 glioma cells, and to inhibit the growth of infective trypanosomes." (PMID 35164094, 2022). "Previous reports in the literature showed that N-indolylethyl-substituted isoquinuclidines with disconnected heteroarene and isoquinuclidine systems of the iboga skeleton act as potent GDNF-releasers in the C6 glioma cell line." (PMID 35164094, 2022). "Another example is that IL-1β stimulates GDNF expression in C6 glioma cells through the inhibitor kappa B (IκB), p38 MAP kinase, p44/p42 MAP kinase and JAK-STAT3 pathways." (PMID 36055989, 2022). "Glial cell-derived neurotrophic factor (GDNF) was originallyisolated from a rat glioma cell-line supernatant and is a potent survival neurotrophicfactor." (PMID 34612709, 2021). "GDNF contributed directly to glioma progression via interacting with its cognate receptor, GDNF receptor-α1." (PMID 34439380, 2021). "GDNF secreted by human and rodent gliomas was found to be a strong chemotactic factor for brain resident macrophages (microglia)." (PMID 34439380, 2021). "Glial cell line-derived neurotrophic factor (GDNF) has been isolated from the conditioned media of a rat glioma cell line on the basis of its trophic activity towards primary cultures of dopaminergic neurons." (PMID 32046031, 2020). "Increase in GDNF levels during treatment is in line with a few previous studies that showed that antipsychotic medications stimulated C6 glioma cells to secrete GDNF, and enhanced GDNF signaling in experimental and clinical settings." (PMID 31420036, 2019). "The aim of the present study was designed to figure out the unique biology of GDNF on the migration and invasion of glioma cells, which provides hitherto unrevealed the mechanism from the perspective of the GA." (PMID 30695072, 2019). "In summary, establishing conditions to test the specific role of GA positioning on directed secretion and glioma cell polarity following GDNF treatment should be further investigated." (PMID 30695072, 2019).